MGST1 (microsomal glutathione S-transferase 1)
Description:
Conjugation of reduced glutathione to a wide number of exogenous and endogenous hydrophobic electrophiles.
Synonyms: GST12; MGST; MGST-I; PMAN
Tractability: Antibody: its Gene Ontology location is reachable by antibodies, with high confidence; UniProt predicts a signal peptide or a membrane-spanning region. PROTAC: ubiquitination databases record sites on it; its protein half-life has been measured.
Target class: Enzyme; Transferase
Gene: Protein-coding gene on chromosome 12 (16,347,115 to 16,609,259, forward strand). Ensembl gene ENSG00000008394.
Subcellular location: Endoplasmic reticulum membrane; Mitochondrion outer membrane
Subcellular location (Human Protein Atlas): Mitochondria; Endoplasmic reticulum
Pathways (Reactome):
Metabolism: Aflatoxin activation and detoxification; Glutathione conjugation
Immune System: Neutrophil degranulation
Gene Ontology:
Molecular function: glutathione peroxidase activity; glutathione transferase activity; protein binding
Biological process: cellular response to lipid hydroperoxide; glutathione transport; cellular oxidant detoxification
Cellular component: mitochondrion; azurophil granule membrane; endoplasmic reticulum; endoplasmic reticulum membrane; membrane; mitochondrial outer membrane; peroxisomal membrane; plasma membrane
Genetic constraint (gnomAD): Loss-of-function variants: 7 observed, 11.17 expected, observed/expected ratio (o/e) 0.63, 90% interval 0.35 to 1.18. The upper end of that interval is the gene's LOEUF score, 1.18, which puts it in group 5 of 6, group 1 being the genes least tolerant of losing a copy. Missense variants: 175 observed, 186.99 expected, observed/expected ratio (o/e) 0.94, 90% interval 0.83 to 1.06. Synonymous variants: 53 observed, 70.19 expected, observed/expected ratio (o/e) 0.76, 90% interval 0.61 to 0.95.
Homologues: Orthologues: chimpanzee MGST1 (100% identical), chimpanzee MGST1 (99% identical), macaque MGST1 (93% identical), dog MGST1 (90% identical), pig MGST1 (90% identical), rat Mgst1 (83% identical), mouse Mgst1 (83% identical), rabbit MGST1 (82% identical), guinea pig MGST1 (78% identical), tropical clawed frog mgst1 (58% identical), zebrafish mgst1.1 (56% identical), zebrafish mgst1.2 (55% identical), and 3 more. Paralogues in human: PTGES (36% identical).
Diseases named in the same sentence as MGST1 in open-access papers:
MGST1 is named in the same sentence as 63 diseases in open-access papers, as found by Europe PMC text mining. Sharing a sentence is not in itself a finding about the gene and the disease. The quoted sentences say what the papers report.
pancreatic cancer (19 papers, 2021 to 2025). "Of note, it has been reported that MGST1 directly interplayed with ALOX5 to cause ferroptosis inhibition via decreasing lipid peroxide production in pancreatic cancer cells." (PMID 39850123, 2025). "Other results obtained in an in vivo xenograft model confirmed that loss of NRF2 or MGST1 can sensitize pancreatic cancer cell xenografts to ferroptosis." (PMID 38539832, 2024). "MGST1 is considered a tumor marker, and its overexpression has been linked to a poor prognosis in several malignancies, and proposed as a potential therapeutic target for pancreatic cancer." (PMID 38169383, 2024). "There have been reports of high expression of MGST1 in pancreatic cancer, glioma, and melanoma, and correlates with poor prognosis in multiple cancers, underscoring its broad relevance." (PMID 40778224, 2025). "Researchers found that MGST1 exerts an anti-ferroptotic effect in pancreatic cancer cells by inhibiting lipid peroxidation." (PMID 40733146, 2025). "Gene knockout experiments have shown that depletion of MGST1 promotes ferroptosis in pancreatic cancer cells." (PMID 40733146, 2025). "To determine the effects of ferroptosis on MGST1 expression, we first treated pancreatic cancer cells with a ferroptosis inducer." (PMID 40076525, 2025). "By inhibiting the effect of MGST1, it can enhance the sensitivity of pancreatic cancer cells to ferroptosis, thereby improving therapeutic efficacy." (PMID 40733146, 2025). "MGST1 was found upregulated during ferroptosis induced by erastin or RSL3 treatments in pancreatic cancer cells." (PMID 38539832, 2024). "Functionally, the loss of MGST1, similar to the loss of NFE2L2, reduces the resistance of pancreatic cancer cells to ferroptosis, making them more vulnerable to this form of cell death." (PMID 39534872, 2024). "In pancreatic cancer, MGST1 binds ALOX5 to inhibit lipid peroxide production during ferroptosis induction." (PMID 39711549, 2024). "MGST1 is considered a novel therapeutic target in pancreatic cancer due to the role it plays in the ferroptosis of pancreatic cancer cells." (PMID 37580393, 2023). "Subsequent studies have found that MGST1 affects lipid peroxidation by regulating ALOX5, and in vivo experiments have confirmed that MGST1 inhibits the growth of xenotransplanted pancreatic cancer mouse tumours." (PMID 34503532, 2021). "Kuang found that high expression levels of MGST1 in pancreatic cancer cells might bind to ALOX5, further reducing lipid peroxidation." (PMID 39160643, 2024). "Four of the top 20 genes are upregulated in cancer stem cells, including Id3 in cancer stem cells of a mouse mammary tumor model and ID3 in intrahepatic cholangiocarcinoma tumors; MGST1 in human pancreatic cancer stem cells; and GPX3 and GSN in quiescent colon cancer stem cells." (PMID 36142331, 2022). "In one study, MGST1 was upregulated in pancreatic cancer cell lines (CFPAC1 and PANC2." (PMID 34503532, 2021). "Therefore, MGST1 emerges as a promising therapeutic target, and targeting the REDOX-sensitive pathway of MGST1 may provide a novel strategy for treating pancreatic cancer." (PMID 40733146, 2025). "Additionally, by analysing The Cancer Genome Atlas (TCGA) database, the overall survival rate of patients with high MGST1 expression was significantly lower than that of patients with low MGST1 expression, suggesting that MGST1 can be used as an indicator of prognosis for pancreatic cancer patients." (PMID 34503532, 2021). "Inducible MGST1 expression, mediated by the activation of the NFE2L2 pathway, inhibits ferroptosis in pancreatic cancer cells." (PMID 39534872, 2024). "For example, NRF2 counteracts ferroptosis by activating microsomal glutathione S-transferase 1 (MGST1), which inhibits ALOX5 in pancreatic cancer cells." (PMID 37886960, 2023). "However, another study reported that MGST1 inhibited ALOX5 expression via a direct interaction, which restrained ferroptosis in pancreatic cancer cells." (PMID 39850123, 2025).
pancreatic cancer (continued). "In addition, MGST1 limits lipid peroxidation via interaction with ALOX5, resulting in inhibition of ferroptotic pancreatic cancer cell death." (PMID 38388563, 2024). "Recent studies have reported that MGST1 can downregulate lipid peroxide production by binding ALOX5 during ferroptosis induction and ultimately inhibit ferroptotic cancer cell death, which is also regarded as a novel therapeutic target in pancreatic cancer." (PMID 35218676, 2022). "Notably, MGST1-mediated protection involves the interaction and partial inactivation of the lipid peroxide-producing enzyme ALOX5, whereas other lipoxygenases like (A)LOX12 or (A)LOX15 do not interact with MGST1, at least in pancreatic cancer cells." (PMID 38539832, 2024).
gastric cancer (12 papers, 2022 to 2025). A primary or metastatic malignant neoplasm involving the stomach. "Elevated MGST1 expression is associated with poor prognosis and ferroptosis resistance in other cancers, including gastric cancer and uterine corpus endometrial carcinoma." (PMID 39534872, 2024). "Recent studies have also focused on tumor promotion in gastric cancer and potential targets for treatment, including MGST1, TTPAL, FBXO11, and IL2RG." (PMID 40186098, 2025). "In gastric cancer cells, MGST1 overexpression leads to the inhibition of autophagy, a process that can trigger autophagy-dependent ferroptosis." (PMID 39534872, 2024). "Upregulated expression of MGST1 is associated with poor prognosis, enhancing the Wnt/β-catenin pathway via regulating AKT, and inhibiting ferroptosis in gastric carcinoma cells." (PMID 39711549, 2024). "Overexpression of MGST1 induces gastric carcinoma cell proliferation by activating the Akt/GSK-3β signaling pathway." (PMID 39711549, 2024). "The MGST1/AKT/GSK-3β axis tightly regulates ferroptosis in gastric cancer cells." (PMID 38562143, 2024). "In summary, the MGST1/AKT/GSK-3β axis modulates ferroptosis by regulating GPX4 levels and activity in gastric cancer cells." (PMID 38562143, 2024). "The elevation of MGST1 has demonstrated enhanced cell proliferation, migration, invasion of trophoblast by the activation of the PI3K/AKT/mTOR pathway, and activation of the AKT/GSK-3β/β-catenin axis in gastric cancer cells." (PMID 40778224, 2025). "MGST1, or microsomal glutathione S-transferase 1, emerges as a critical player in conferring resistance to ferroptosis in cancer cells, particularly illustrated in the context of SGC7901 gastric cancer cells." (PMID 38562143, 2024).
melanoma (6 papers, 2019 to 2025). A malignant, usually aggressive tumor composed of atypical, neoplastic melanocytes. "Here we reported that MGST1 is a risk factor of melanoma and the detailed mechanism deserved further investigations." (PMID 33014847, 2020). "Targeting MGST1 alters the redox balance and suppresses metastatic progression in melanoma, thereby improving the efficacy and safety of chemotherapy and immune checkpoint inhibitors." (PMID 40778224, 2025). "Targeting MGST1 has shown to alter the redox balance, limit metastases, and enhance the efficacy of chemo- and immunotherapies in melanoma." (PMID 39501138, 2024). "Based on WARS and MGST1, MRGs signature was established to predict melanoma prognosis according to the formula: MRGs signature = (−0.139 × expression of WARS) + (0.122 × expression of MGST1)." (PMID 33014847, 2020). "WARS was strongly positive in melanoma tissue, while MGST1 was weakly positive in normal skin tissue." (PMID 33014847, 2020). "Among genes that were upregulated by SIRT2 silencing were those that are downregulated in aggressive melanoma cells (e.g., MGST1 is upregulated in the SSW30 and SSM15 clones)." (PMID 31091806, 2019). "Elevated MGST1 expression has been observed in malignant and drug-resistant melanomas." (PMID 39501138, 2024). "Knockdown of MGST1 enhanced the efficacy of CD8+ T cells in killing B16 melanoma cells in vitro." (PMID 39501138, 2024). "WARS and MGST1 were highly expressed and downregulated in GSE15605 melanoma datasets, separately." (PMID 33014847, 2020). "Additionally, microsomal glutathione S-transferase 1 (MGST1), which requires GSH as a cofactor, has been demonstrated to promote melanin biosynthesis and melanosomal eumelanin accumulation in melanoma models, linking glutathione metabolism to pigment formation." (PMID 41155296, 2025). "The role of WARS and MGST1 in melanoma has not been reported." (PMID 33014847, 2020).
glioma (4 papers, 2022 to 2025). A benign or malignant brain and spinal cord tumor that arises from glial cells (astrocytes, oligodendrocytes, ependymal cells). "MGST1 participates in the growth, migration, invasion, and epithelial–mesenchymal transition of glioma cells by acting as a target of miR-379-5p." (PMID 36568515, 2022). "Although MGST1 was found to exert a role in reactive intermediate-induced injury, oxidative stress, aging, glioma, and lung adenocarcinoma, its function in PE remains to be explored." (PMID 36568515, 2022). "This highlights the potential of MGST1 as a target for overcoming chemoresistance in glioma." (PMID 39534872, 2024). "In glioma cells, ZNF384-mediated MGST1 expression contributes to resistance against the chemotherapeutic agent temozolomide by negatively regulating ferroptosis." (PMID 39534872, 2024).
lung cancer (4 papers, 2015 to 2025). A malignant neoplasm involving the lung. "MGST1 overexpression has been demonstrated in various cancers (e.g., prostate cancer and lung cancer) and has been associated with high metastatic potential and chemoresistance." (PMID 26091520, 2015). "Increased abundance of ARRB1, as well as FBXO11, LYZ, RPS6KB1, and SYNGR2 have comparable oncogenic effects in hepatocellular carcinoma, and MGST1 and RPS6KB1 have noted oncogenic roles in various lung cancers." (PMID 40186098, 2025).
pancreatic ductal adenocarcinoma (4 papers, 2024 to 2025). An infiltrating adenocarcinoma that arises from the epithelial cells of the pancreas. "Inhibition of ALOX5 operated by the microsomal glutathione S-transferase 1 (MGST1) was observed to be consistent in human pancreatic ductal adenocarcinoma (PDAC) cell lines, remarking on ALOX5 role as a positive regulator of ferroptosis." (PMID 37132605, 2024). "Conversely, re-expression of MGST1 in NFE2L2-knockdown pancreatic ductal adenocarcinoma cells can restore their resistance to ferroptosis, underscoring the critical role of MGST1 in ferroptosis regulation." (PMID 39534872, 2024). "Notably, MGST1 has been identified as a potential prognostic marker for poor outcomes in patients with pancreatic ductal adenocarcinoma (PDAC) and several other tumors." (PMID 40076525, 2025).
breast cancer (3 papers, 2022 to 2023). A primary or metastatic malignant neoplasm involving the breast. "And TAGLN, ASPN, KRT19 and MGST1 have important roles in the prognosis, invasion, metastasis and drug resistance of breast cancer." (PMID 37470685, 2023). "RT-qPCR experiments confirmed that our breast cancer cell lines express all three MGSTs (MGST1/MGST2/MGST3) at steady states." (PMID 36293074, 2022). "Here, we show that human MDA-B02 breast cancer cells produce CysLT through mechanisms involving microsomal glutathione-S-transferase 1/2/3 (MGST1/2/3) and that can modulate cancer cell–platelet interactions via platelet–CysLT1R." (PMID 36293074, 2022).
colorectal cancer (3 papers, 2019 to 2025). A primary or metastatic malignant neoplasm that affects the colon or rectum. "For instance, studies have demonstrated involvement of ARRB1, MGST1, and TTPAL in colorectal cancer, leading to increased cancer cell proliferation and subsequent poor prognosis." (PMID 40186098, 2025).
endometriosis (3 papers, 2021 to 2024). The growth of functional endometrial tissue in anatomic sites outside the uterine body. "As an indicator of ZEN-induced oxidative stress in gilt ovaries during HS, MGST1 is increased in oocytes from endometriosis patients, and is increased by antioxidant treatment of PCOS in rats." (PMID 38666409, 2024). "Among the top 20 genes, APOE, DUSP1, MGST1, G0S2, ID4, WEE1, and H2AFZ expression levels were upregulated in the oocytes of patients with endometriosis." (PMID 33467661, 2021).
lung adenocarcinoma (3 papers, 2020 to 2025). A carcinoma that arises from the lung and is characterized by the presence of malignant glandular epithelial cells. "Knockdown of MGST1 inhibits lung adenocarcinoma cell proliferation and induces apoptosis via inactivation of the AKT/GSK-3β signaling pathway." (PMID 40778224, 2025). "Another study also demonstrated that MGST1 silencing attenuated the proliferation and promoted the apoptosis of lung adenocarcinoma cells." (PMID 36568515, 2022). "Further, Zeng and his colleagues demonstrated MGST1 knockdown could inhibit lung adenocarcinoma cell proliferation by inactivating the AKT/GSK-3β pathway signaling and promote cell apoptosis by regulating the mitochondrial apoptosis pathway related proteins." (PMID 33014847, 2020).
prostate carcinoma (3 papers, 2015 to 2020). A carcinoma that arises from epithelial cells of the prostate gland. "Moreover, MGST1 overexpression was correlated to higher metastatic potential in human prostate cancer." (PMID 33014847, 2020). "MGST1 was linked with the invasion and chemoresistance in EOC.The loss of AKR1C2 was responsible for the advancement of prostate cancer, but the inactivation of this gene may be associated with the development of EOC." (PMID 30970615, 2019).
Sepsis (3 papers, 2016 to 2025). Sepsis is defined as life-threatening organ dysfunction caused by a dysregulated host response to infection. "In the training dataset, the expression of LILRA5, MGST1, PLBD1, and S100A9 was upregulated significantly in the sepsis group compared to the normal group." (PMID 40792106, 2025). "LILRA5, MGST1, PLBD1, and S100A9 were selected as hub genes and significantly upregulated in sepsis." (PMID 40792106, 2025). "Moreover, in the test datasets, the expression of LILRA5, MGST1, PLBD1, and S100A9 was significantly elevated in the sepsis group." (PMID 40792106, 2025).
atherosclerosis (2 papers, 2022 to 2023). A disease characterized by the build-up of fatty material and calcium deposition in the arterial wall resulting in partial or complete occlusion of the arterial lumen. "The results of RNA sequencing analysis showed that many antioxidant genes were enriched in Fluid shear stress and atherosclerosis pathway, including MGST1, GSTM3, GSTA1, SOD2 and GSTA4." (PMID 36978937, 2023).
cervical cancer (2 papers, 2022 to 2025). A primary or metastatic malignant neoplasm involving the cervix. "Precious studies have shown that MGST1 was up-regulated in bendamustine hydrochloride-resistant lymphoma cells, doxorubicin-resistant cervical cancer cells, and DDP-resistant NSCLC cells." (PMID 39850123, 2025).
colon cancer (2 papers, 2010 to 2022). "Specifically, MGST1 (Microsomal glutathione S-transferase 1; EntrezGene ID: 4257) is markedly down-regulated (t-test nominal p-value = 6.9×10−5, 65.0% average reduction compared to control) and certain MGST1 polymorphisms have been associated with increased colon cancer risk." (PMID 21085593, 2010).
diabetes (2 papers, 2024 to 2026). "MGST1 is considered as a key ferroptosis-related gene in type 2 diabetic mellitus." (PMID 39711549, 2024). "In type 2 diabetes, MGST1 was identified as the potential ferroptosis-related gene in islet beta cells dysfunction (IBCD) of type 2 diabetic mellitus (T2DM) by combing large patient samples of islet issue sequencing datasets and specificity of islet single-cell sequencing dataset." (PMID 39711549, 2024). "Diabetes significantly decreased HSPB1 and MGST1 levels and increased ferroptosis compared to normal group." (PMID 39711549, 2024).
endometrial carcinoma (2 papers, 2022 to 2024). A malignant tumor arising from the epithelium that lines the cavity of the uterine body. "MGST1, a ferroptosis-associated MGST1 gene, is highly expressed in endometrial carcinoma, resulting in poor outcome." (PMID 38385087, 2024). "Since microsomal glutathione S-transferase 1 (MGST1) is a ferroptosis suppressor, the expression of MGST1 was higher in endometrial cancer than in the normal tissues." (PMID 35847989, 2022). "Therefore, MGST1 can serve as a predictive factor for the prognosis of endometrial cancer." (PMID 35847989, 2022).
Ewing sarcoma (2 papers, 2019 to 2022). A small round cell tumor that lacks morphologic, immunohistochemical, and electron microscopic evidence of neuroectodermal differentiation. "Through our investigation, we confirmed that MGST1 and the new marker COL6A2 are both produced by doxorubicin-resistant cells and demonstrated clinical significance for the survival of patients with Ewing sarcoma." (PMID 36428591, 2022).
Insulin resistance (2 papers, 2022 to 2025). Increased resistance towards insulin, that is, diminished effectiveness of insulin in reducing blood glucose levels. "In addition, Rha treatment modulated insulin resistance and increased gene expression of antioxidant enzymes (Cat, Sod2, Gpx3, Mgst1, Prdx3, Gsta4, Gsr, and Sod1) in the ovaries of the PCOS rats." (PMID 35663203, 2022).